CRP (C-reactive protein)
Diseases named in the same sentence as CRP in open-access papers (continued):
Sharing a sentence is not in itself a finding about the gene and the disease.
Fever (158 papers, 2007 to 2026). Body temperature elevated above the normal range. "Fever was associated with elevated plasma levels of interleukin-6 (IL-6) (224 pg/mL) and C-reactive protein (CRP) (117.6 mg/L)." (PMID 40705122, 2025). "Fever and elevated C-reactive protein levels were significantly associated with antibiotic prescription." (PMID 41153485, 2025). "Fever, CRP levels, and decreased testicular blood flow are risk factors for unfavorable testicular outcomes in pediatric patients with AE." (PMID 40884544, 2025). "Fever and elevated CRP levels on admission were independently associated with inappropriate antibiotic use." (PMID 41153485, 2025). "In line with previous studies, our study indicated that fever and laboratory results (elevation of white blood cell count and C-reactive protein level) were more commonly associated with infectious pneumonia." (PMID 36461012, 2022). "Serum Ca, Fe, Se, Zn correlated positively with SpO2, being inversely associated with fever, lung damage, and C-reactive protein concentrations." (PMID 33920813, 2021). "Together, these data indicate that the kinetics of hepcidin perturbations and the associated hypoferremia during acute S. Typhi infection mirror typhoid-associated fever and CRP induction." (PMID 26394303, 2015). "This study suggests that PCT, when measured periodically, is a more useful diagnostic inflammation parameter in pediatric neutropenic-fever patients than CRP." (PMID 18034890, 2007). "The cause of pyrexia, increased CRP and Ferritin, hypotension and tachycardia could be attributed to CRS." (PMID 34518515, 2021). "Fever, elevated C-reactive protein (CRP) and white blood cell (WBC) levels, reduced CSF glucose, and increased CSF protein levels were significantly more frequent in the infection group (p<0.001)." (PMID 41727797, 2026). "Fever was uncommon (15.9%), and inflammatory markers were frequently normal (white blood cell counts in 81.1%, C-reactive protein levels in 60.4%) and abnormal in 69.2% for erythrocyte sedimentation rates and in 53.8% for platelet count." (PMID 41753800, 2026). "Fever, elevated CRP, and elevated WBC count are specific reference indicators of systemic signs of inflammatory." (PMID 40989157, 2025). "The acute form is clinically characterised by hyperesthesia along the vertebral column and particularly on the neck, a stiff gait, pyrexia, and increased serum C-reactive protein (CRP)." (PMID 40431569, 2025). "Compared to the BCG-itis group, the BCG-D group exhibited significantly higher rates of fever, hepatosplenomegaly, elevated white blood cell counts, neutrophil counts, and C-reactive protein (CRP) levels." (PMID 40470261, 2025). "Our findings suggest that fever, CRP levels, and decreased testicular blood flow are predictors of poor outcomes." (PMID 40884544, 2025). "Fever (p = 0.001), C-reactive protein (CRP) levels (p = 0.002), and decreased testicular blood flow on ultrasonography (p < 0.001) were significantly associated with poor testicular outcomes." (PMID 40884544, 2025). "Fever in AS patients typically indicates inflammatory activity and is frequently accompanied by elevated CRP, ESR, and local or systemic inflammatory responses." (PMID 41019081, 2025). "Fever and increased erythrocyte sedimentation rate or C-reactive protein levels are seen in about 50% of individuals." (PMID 39239002, 2024). "The high bacterial load group had high fever, high thermal peak, long duration of fever, and elevated levels of C-reactive protein." (PMID 37426001, 2023). "Fever decrease (day 4), C-Reactive protein CRP levels (day 6), the intensity of symptoms (day 8), CGS score (day 10), and death on day 30 were all secondary outcomes." (PMID 35462919, 2022). "The mean ± 2 SD of CRP level was higher in the KD group than in the fever group (8.5 ± 6.0 mg/dL vs. 3.4 ± 5.0 mg/dL, p < 0.001)." (PMID 35052869, 2022).
Fever (continued). "By visual analysis of routine laboratory values of melanoma patients developing pyrexia under BRAF/MEK inhibition, we observed that CRP rises and leukocyte as well as thrombocyte counts drop simultaneously before and during pyrexia." (PMID 36006943, 2022). "There is positive correlation between fever and C-reactive protein, the higher the C-reactive protein level is, the higher the incidence of postoperative fever will be." (PMID 36371192, 2022). "The pyrexia score primarily assesses changes of analysed laboratory values only in the expected direction, i.e., rise of CRP and LDH and fall of thrombocytes and leukocytes." (PMID 36006943, 2022). "Graphical visualization of time series of laboratory values suggested that a rise in C-reactive-protein, in parallel with a fall of leukocytes and thrombocytes, were indicative of pyrexia." (PMID 36006943, 2022). "Fever was present in 14 patients (21%) at admission and mean value of C-reactive protein (CRP) was 162 mg/l." (PMID 34185186, 2021). "Anicteric leptospirosis should be a differential diagnosis in patients presenting with pyrexia, myalgia, and headache who have elevated CRP and abnormal urinalysis." (PMID 34306102, 2021). "The inflammatory syndrome characterised by fever, CRP and leucocytosis was present in 64.68% and 56.74%, respectively." (PMID 32731610, 2020). "A 5-year-old girl (MEC-12), who had shown a slightly elevated WBC and CRP in blood screening just before medication, had a low-grade fever (pyrexia) 4 hours after administration of meclizine." (PMID 32282831, 2020). "This decreased mRNA expression of METTL14 was associated with WBC and M; this decreased mRNA expression of ALKBH5 was associated with CRP, N%, L%, NLR, C3, and fever; and the decreased mRNA expression of YTHDF2 was associated with L%, NLR, C3, and fever." (PMID 32583611, 2020). "On postoperative day (POD) 10, the patient had pyrexia (38.4 °C), and C-reactive protein (CRP) was increased to 16.22 mg/dL." (PMID 30643997, 2019). "Fever duration, C-reactive protein (CRP), blood neutrophil count and blood lymphocyte count are significantly different between mild MPP group and severe MPP group." (PMID 31780733, 2019). "In this study, CRP in the fever group was significantly higher than that in the no-fever group, suggesting the inflammatory response was more pronounced in the fever group." (PMID 30847312, 2019). "Fever, erythema, eschar, and elevated C-reactive protein (CRP) are characteristic clinical features of the disease." (PMID 29968555, 2018). "Fever, elevated absolute neutrophilic count and positive C-reactive protein raise the probability of ascitic fluid infection by 3.88, 9.15 and 4.48 times respectively." (PMID 30289914, 2018). "Evidence of SIR was detected in 218 in that they had pyrexia and/or an elevated CRP at the time of admission." (PMID 29540199, 2018). "Using a univariate analysis, we found that the number of days with a fever before diagnosis, total fever duration, CRP levels, and ln-ROM inversely correlated with %FMD." (PMID 29426283, 2018). "Fever, abdominal pain, positive C-reactive protein and elevated absolute neutrophilic count are strong predictors of ascitic fluid infection." (PMID 30289914, 2018). "Significant differences were observed in Fever process, leukocyte count, C-reactive protein>38 mg/l and C-reactive protein>100 mg/l between single and co-infections (P < 0.05)." (PMID 29970200, 2018). "The two patients 10 and 14 who experienced myalgia and pyrexia accompanied by increased CRP also showed elevated IL-6 levels, with the highest levels 67.23 pg/mL and 87.96 pg/mL, respectively." (PMID 29268708, 2017). "A total of 22 AEs were reported in the four patients and 10 of them were judged to have a “Probable/Certain” relationship to the study drug; 9 infusion-related reactions with pyrexia, chills and body ache and one case of C-reactive protein increase." (PMID 28158311, 2017).
Fever (continued). "The patient numbers 10 and 14 experienced myalgia and pyrexia accompanied by increased CRP and had the highest temperature 38.9 °C and 38.8 °C, respectively." (PMID 29268708, 2017). "Clinical response was initially characterized by a swift reduction of fever, neutrophilia (7,000/mm3), CRP (10 mg/L, normal values <6), and ferritin (112 ng/mL, normal values 15–150 ng/mL)." (PMID 28232838, 2017). "There was a moderate correlation between PCT and CRP levels in the fever cohort (Spearman rho = 0.472; p = <0.001) and between PCT and neutrophil count (Spearman rho = 0.513; p = <0.001)." (PMID 29179755, 2017). "Of note, the incidence of CRP increased, and the occurance of pyrexia and myalgia in the highest dose group were high." (PMID 29268708, 2017). "6Tsuji found that IVC clotting caused an inflammatory reaction in half of the patients who presented with pyrexia and elevation in d-dimer levels and inflammatory markers (white cell count, C-reactive protein)." (PMID 26836612, 2016). "Patients in the fever group had markedly higher mean values of ESR (40.8 (29.0) vs. 26.4 (20.1) mm/h), CRP (20.7 (29.5) vs. 9.7 (14.3) mg/dL), and platelets (353.2 (101.1) ×109/L vs. 275.6 (87.4) ×109/L) than the non-fever group (all p<0.05)." (PMID 26030261, 2015). "The commonest symptoms and signs among our cohort were diarrhoea, a rising CRP, white cell count >15×109/L and pyrexia >38.5°C." (PMID 23300561, 2012). "The case we describe showed a pronounced immunoresponse with elevated CRP, low-grade pyrexia, complement consumption and an immune infiltrate in the liver." (PMID 23231599, 2012). "Current common clinical indicators of infection include pyrexia, white blood cell counts, C-reactive protein (CRP) and procalcitonin (PCT)." (PMID 21356122, 2011). "A 21 year old female was admitted with pyrexia, right iliac fossa tenderness and an elevated C-reactive protein (CRP)." (PMID 18783617, 2008). "Fever, elevated C-reactive protein and leukocytes, and use of respiratory support were common." (PMID 41612523, 2026). "Notably, the top-ranked features span multiple clinical domains, including a definitive radiological indicator, key physical examination findings (Rhonchus, Prolonged expiration), a core symptom (Fever), and an inflammatory biomarker (CRP)." (PMID 40941745, 2025). "In several patients treated at the Department of Dermatology at the University Hospital of the RWTH Aachen, Germany, we observed an increase of C-reactive protein (CRP) in parallel with a decrease of leukocyte and thrombocyte counts at the time of pyrexia and sometimes already before pyrexia." (PMID 36006943, 2022). "Fever, elevated CRP, elevated CSF protein, and an abnormal MRI were more common in IE." (PMID 36237630, 2022). "Fever and impaired general condition were more frequent as well as higher CRP, LDH, and neutrophil counts in patients with malignancy, infection, and other inflammatory diseases compared to groups of other non-inflammatory diseases and the group without diagnosis." (PMID 35903938, 2022). "However, it is difficult to differentiate between CRS and infections due to the similar clinical manifestations, such as pyrexia and the elevated levels of pro-inflammatory cytokines and C-reactive protein (CRP)." (PMID 35757715, 2022). "Are there any other fever-related factors that influence ESR more than CRP in patients with PMR?" (PMID 35888074, 2022). "Fever (55.1% vs. 14.2%, p < 0.001), elevation of white blood cell count (34.8% vs. 20.1%, p = 0.004), and elevation of C-reactive protein level (69.1% vs. 41.8%, p < 0.001) were more commonly observed in patients with infectious pneumonia than those with pneumonic-type IMA." (PMID 36461012, 2022). "CRP was found to be higher in dogs displaying pyrexia, regardless of the underlying cause (median 140 μg/mL) in 825 dogs, but with no linear correlation." (PMID 36290272, 2022).
Fever (continued). "Transient increases in levels of C-reactive protein, ferritin (and decrease in iron), IL-6, and/or IL-8 with pyrexia and vomiting during dose escalation in three patients were characterized by investigators as acute phase reactions and led to dose adjustments at the next infusion." (PMID 33875845, 2021). "However, current common clinical indicators of infection include pyrexia, white blood cell counts, C-reactive protein (CRP), and procalcitonin (PCT) are still unsatisfactory." (PMID 23935252, 2013). "Fever and/or elevated CRP/WBC and intra-abdominal fluid collection on CT-imaging or ultrasound." (PMID 22236534, 2012). "One explanation for this finding may be that the sensitivity of the NADPH-oxidase system to LPS is much higher compared to induction of neutrophilia or fever or CRP, such that 1 μg of LPS gives already a maximum response." (PMID 22496751, 2012). "The CRP was able to correctly identify 83.3% and 81.8% of the neonates with positive blood culture who were born to mothers with foul smelling amniotic fluid and peri-partum pyrexia respectively." (PMID 22958461, 2012). "This walled-off process with a foreign body present, however, elicited either a localized inflammatory reaction powered with the microbial burden of the upper gastrointestinal tract as well as a systematic response manifested with fever, leucocytosis and C-reactive protein level elevation." (PMID 22919520, 2012). "In this report we discussed a patient who had poorly differentiated HCC with pyrexia and high CRP." (PMID 19707535, 2009). "Fever was reported in 46.0% of patients, and laboratory findings revealed a median WBC count of 10,730 cells/mm3 (IQR: 8,030–13,900), CRP levels of 2.5 mg/dl (IQR: 0.8–7.0), and ESR of 32 mm/h (IQR: 17–49)." (PMID 40005524, 2025). "Fever duration was longer in the delayed-onset group (2.9 ± 1.6 days), and inflammatory markers, including WBC, ESR, and CRP, were significantly higher in the delayed-onset group (p < 0.01)." (PMID 41463745, 2025). "Compared to both healthy and fever control groups, the KD group exhibited significantly elevated WBC, NEU, PLT, CRP, ESR, PCT, and ALT, as well as decreased levels of Hb, ALB, and AST (all p < 0.05)." (PMID 40044787, 2025). "We found that PCT, CRP and ESR levels were low in patients with central fever and high in patients with infectious fever." (PMID 38681106, 2024). "Fever is present in 62.1% of cases, along with elevated WBC, CRP, and erythrocyte sedimentation rate (ESR) levels, indicating infection and inflammation." (PMID 39280445, 2024). "Fever was significantly (p < 0.001) more common in the fistula group, and ratios (POD 7 to 3) of WBC, CRP, neutrophils, and neutrophils-to-lymphocytes (NLR) were significantly higher (all p ≤ 0.001) in the fistula group than in the no fistula group." (PMID 36902638, 2023). "In patients with solid tumors admitted to hospital for pyrexia, we showed that the combination of baseline PCT and CRP/PCT ratio measurements display good performance for discriminating between infection-related and cancer-related fever." (PMID 33777975, 2021). "In our study, we found that fever, active arthritis, sJADAS-27 score, white blood cell count, ESR, and CRP can be relieved after 2 weeks of TCZ treatment." (PMID 34820342, 2021). "CRP, WBC, platelet, neutrophil, ALT, ALP, GGT, and creatinine before EBUS-TBNA in the Fever group were significantly higher than in the non-Fever group (all, p < 0.001)." (PMID 31935941, 2020). "Fever, elevated ANC and CRP increased the probability of AFI 3.88, 9.15 and 4.48 times respectively." (PMID 30289914, 2018). "In fever onset samples, the age of patients was 51 ± 17.9 (n = 38), 39.5% females, WBC = 1.2 ± 3.1 (n = 33), ANC = 0.4 ± 1.2 (n = 29), CRP = 51.6 ± 37.5 (n = 30)." (PMID 26270467, 2015). "Fever was reported in half of our patients, whilst the mean WBC and CRP values were raised." (PMID 40095044, 2025). "We analyzed the correlations among CRS, fever, PCT, IL-6, and CRP." (PMID 38956649, 2024).
Fever (continued). "In our study, C acnes IE was characterized by absence of fever (66.7%) and close to normal CRP levels." (PMID 37436747, 2023). "Fever persisted without significantly increasing of C-reactive protein (CRP) after 5 days of intravenous treatment with azithromycin and cephalosporins prescribed by other hospitals." (PMID 36414954, 2022). "Fever is generally absent, local inflammatory signs or a fistula are observed in less than one-third of the patients with these hip or knee infections and C-reactive protein (CRP) can be normal or only slightly elevated." (PMID 36551458, 2022). "PS based on the four parameters CRP, LDH, leukocyte and thrombocyte numbers, were statistically significantly higher in pyrexia patients, differentiated between groups (F = 20.8; p = <0.0001) and showed a significant predictive value for the diagnosis of pyrexia (F = 6.24; p = 0.013)." (PMID 36006943, 2022). "In many pyrexic patients, CRP values were only determined after pyrexia had occurred, so we often lacked data points for the pre-pyrexic time cluster." (PMID 36006943, 2022). "Fever is more common in patients with GCA than PMR, and CRP levels in Horton patients with fever at onset may be within normal results." (PMID 35888074, 2022). "IUO: Inflammation of unknown origin, FUO: Fever of unknown origin, SD: Standard deviation, CRP: C-reactive protein, ESR: erythrocyte sedimentation rate, LDH: lactate dehydrogenase." (PMID 35592192, 2022). "Fever was more common, the time from symptom onset to biopsy was shorter, and the serum C-reactive protein level was higher in the AFOP group than in the non-AFOP group." (PMID 33793625, 2021). "The most common adverse events (AEs) were grade 1 flu-like symptoms which did not require any intervention, including pyrexia (40%), fatigue (33.33%), C-reactive protein (CRP) increased (46.67%), myalgia (40%), abdominal pain (33.33%), and nausea (20%)." (PMID 29268708, 2017). "Fever and paravertebral abscesses were less common and erythrocyte sedimentation rate (ESR) and CRP levels were lower in CNPS than in CPPS, which could be explained by the lower bacterial burden in CNPS." (PMID 27733126, 2016). "The radiographic intrapulmonary consolidation subsequently disappeared, C-reactive protein (CRP) became negative, and pyrexia improved." (PMID 26943430, 2015). "We discuss a patient who had poorly differentiated HCC with pyrexia and high CRP in laboratory data, which are not commonly observed in the usual HCC." (PMID 19707535, 2009). "Importantly, none of the 3HP-treated animals exhibited elevated CRP levels, pyrexia, or wasting after SIV coinfection and did not need to be euthanized due to disease progression." (PMID 35862216, 2022). "Most of the fever cases are of viral origin; however, the most common markers, such as leucocyte, neutrophil count, or C-reactive protein, are not sensitive or specific enough to distinguish the etiology of fever, especially if children present at the early phase of infection." (PMID 36362702, 2022). "While high CRP levels were significantly associated with NF, we could not assess whether elevation in CRP could reliably distinguish between engraftment fever versus infection." (PMID 30202676, 2018). "Furthermore, the FN‐category correlated with inflammation‐related proteins such as CRP (R = 0.44), SAA1 (R = 0.44), and SAA2 (R = 0.40), and their levels were indeed increased in samples obtained from patients with mild‐FN and complicated‐FN compared to non‐fever patient samples." (PMID 39441646, 2024).